CD4 (CD4 molecule)
Diseases named in the same sentence as CD4 in open-access papers (continued):
Sharing a sentence is not in itself a finding about the gene and the disease.
malaria (continued). "In this report, we leverage pre-existing gene expression data from malaria parasites to identify candidate CD4+ T cell epitopes in P. falciparum antigens that are primarily expressed during the liver stage of development." (PMID 39993000, 2025). "Plasmodium-specific CD4+ T cells differentiate into effector and memory subsets during experimental malaria, via mechanisms that remain incompletely characterised." (PMID 40132035, 2025). "Taken together, our analysis revealed Myo1f and Prr13 expression were upregulated and maintained in specific effector and memory CD4+ T cell subsets during experimental malaria." (PMID 40132035, 2025). "Frequent episodes of symptomatic malaria can lead to poorer health outcomes, including anemia, an increase in plasma viral load, and a drop in CD4 count in HIV-infected individuals." (PMID 40896267, 2025). "However, among PLHIV, the risk of malaria treatment failure (unadjusted for recrudescence or reinfection) on day 45 was found to be 2.24-fold higher among those with CD4 cell count < 300 cells/μL compared to those with CD4 cell count ≥ 300 cells/μL (RR 2.24, 95%CI 1.20–4.17, p-value = 0.01)." (PMID 40380136, 2025). "On the other hand, pre-existing malaria promoted SIV disease progress by producing more CD4+CCR5+ T cells for SIV replication." (PMID 40950582, 2025). "In the malaria immune regulatory network, CD4+ T cells and macrophages constitute key roles: IFN-γ secreted by Th1 cells plays a central role in controlling acute infection, while macrophages eliminate Plasmodium through phagocytic killing mechanisms." (PMID 41422632, 2025). "The literature attests that HIV patients are susceptible to malaria infection due to reduced immunity resulting from the depletion of clusters of differentiation 4 (CD4) cells by the virus, which consequently reduces the production of malaria antibodies." (PMID 40519803, 2025). "Co-infected animals showed fewer numbers of total CD4+ T cells, CD4+CD28highCD95high central memory T cells, and CD4+CD28lowCD95− naive T cells than those infected solely with malaria." (PMID 40950582, 2025). "H3K27Ac profiles from Roadmap data, revealed active regulatory elements at the ATP2B4 Epromoter, containing malaria-associated SNPs and the LAX1 promoter in CD4+ T cells." (PMID 40441141, 2025). "Cotrimoxazole prophylaxis is indicated at any CD4 in areas with high incidence of malaria and severe bacterial infections, and at CD4 below 350 cells/μL in other areas, but recommended at CD4 below 200 cells/μL in several countries." (PMID 39046150, 2025). "We were nevertheless surprised that our bulk and single-cell RNAseq data both suggested that TH1-polarized CD4+ T cells acquired transcriptional features of cytotoxicity during a first-in-life malaria episode." (PMID 40214640, 2025). "Using this approach, we were able to demonstrate P. falciparum epitope-specific CD4+ T cell responses in the peripheral blood of 67% of malaria-exposed Ugandan children." (PMID 39993000, 2025). "Collectively, these data demonstrated, firstly, the utility of our approach for examining cell-intrinsic gene function in Plasmodium-specific CD4+ T cells in vivo, and secondly that cMaf is essential for Tfh differentiation in experimental malaria." (PMID 40132035, 2025). "Ultimately, the multifaceted roles of CD4+ T cells—ranging from intracellular parasite control by Th1 cells to antibody production mediated by Tfh cells—highlight their indispensability in malaria immunity." (PMID 39861032, 2025). "A growing body of evidence indicates that malaria-specific CD4+ T cells respond against pre-erythrocytic forms of P. falciparum, and their functionality correlates with protection from reinfection in human studies." (PMID 39993000, 2025). "These lineages play distinct roles in adaptive immunity, with CD4+ T cells being central to protective responses during the erythrocytic stage of malaria." (PMID 39861032, 2025).
malaria (continued). "Collectively, these data show that the T cell response to a first-in-life malaria episode is dominated by heterogeneous CD4+ T cells that present with unusual features of terminal differentiation and cytotoxicity." (PMID 40214640, 2025). "Evidence of malaria-induced immunosuppression was observed in our data in cytokine secretory profiles, where CD4 and CD8 T-cell responses were dominated by upregulation of IL-10 and downregulation of IFN-γ–secreting cells." (PMID 41285032, 2025). "In this study, we demonstrate here that chronic malaria antigen exposure changes the host metabolic, cytokine, peripheral CD4+, and T regulatory cell immune response to acute infection." (PMID 40726977, 2025). "This was also observed in multiple publications that show that CD4+ T cells in malaria-experienced children were concurrently producing IL-10 and IFN-γ." (PMID 40337867, 2025). "For example, most malaria vaccine candidates had seven times the immunogenicity of humoral immune cells compared to CD4+ and CD8+ cells, which appeared only two times (7.14%)." (PMID 39854359, 2025). "Previous studies have also shown that CD4+ T cells from individuals in malaria-endemic areas also display a marked increase in IL-10, which was dependent on malaria infection experience." (PMID 40337867, 2025). "Together, these results suggest that high circulating levels of IL-10 produced by CD4+ T cells contribute to subclinical patent parasitemia by suppressing an otherwise robust inflammatory response in a mouse model of subclinical malaria." (PMID 40972121, 2025). "To explore this further, we sorted CD4+ T cells with an effector or effector memory phenotype (CCR7neg CD45RAneg), which has been shown to dominate the adaptive response to malaria in a naive host." (PMID 40214640, 2025). "Within the T-cell lymphocyte subpopulations, children with uncomplicated malaria had altered CD4 and CD8 T-cell subsets compared to community controls." (PMID 41285032, 2025). "Our data therefore reveal that the unique feature of a first-in-life malaria episode is fulminant CD4+ T cell activation and that this response is attenuated after a single infection." (PMID 40214640, 2025). "Using specimens from Ugandan children living in a high malaria transmission area, we confirmed that several of these epitopes are in fact targets of CD4+ T cells in naturally developed immune responses." (PMID 39993000, 2025). "Treatments against malaria more commonly fail in HIV-positive individuals with lower CD4-cell counts and anemic patients compared with those who are HIV-negative." (PMID 40896267, 2025). "From the study outcome, it was seen that more participants in the control group had normal CD3+, CD8+, and CD4+ cells as compared with the malaria patients who showed depletion in the cells." (PMID 38987710, 2024). "The findings provide mechanistic insight into posttranslational regulation of STAT3 in Tfh cell development and function, which broadens our understanding of the molecular regulation of effector CD4+ T cell responses in blood-stage malaria." (PMID 39024388, 2024). "CD4+ T cells are the major drivers of protection against blood-stage infection in mouse model of malaria." (PMID 39211036, 2024). "A higher prevalence of malaria was observed among children with CD4 cells <200cells/μL and the odds were three times higher among those children with CD4 cells <200cells/μL." (PMID 39559371, 2024). "The type I IFNs play a more complex role during malaria, such as promoting parasite clearance in the liver stage, suppressing IFNγ production of parasitic-specific CD4+ T cells, and promoting IL-10 producing Th1 cells." (PMID 38715061, 2024). "The highest malaria parasite prevalence was observed in children with CD4 T cell count <200 cells/μl (n = 33; 48.53 %), followed by those with CD4 T cell count between 200 and 349 (n = 17; 37.78 %)." (PMID 39559371, 2024).
malaria (continued). "Adjusting for transcriptome-derived naïve CD4 T cell proportions resulted in the smallest number of DEGs in the baseline to recovery contrast and the largest number in the baseline to malaria or malaria to recovery compared to any other model." (PMID 38992677, 2024). "In summary, we have elucidated the biological effects of RACK1 on CD4+ T cell responses and subsequent humoral immunity in a murine malaria model." (PMID 39024388, 2024). "CD4+ T cells play an integral role in the acquisition and maintenance of protective immunity to blood-stage malaria." (PMID 39024388, 2024). "CD4+ T cells are central mediators of protective immunity to blood-stage malaria, particularly for their capacity in orchestrating germinal center reaction and generating parasite-specific high-affinity antibodies." (PMID 39024388, 2024). "Defining regulators that manipulate CD4+ T cell activities will facilitate the development of optimal interventions against malaria." (PMID 39024388, 2024). "Our study uncovered a cooperative interaction between γδ T cells and cDC1 for adequate Th1 cell commitment of Plasmodium-specific CD4+ T cells in the initial phase of malaria." (PMID 39211036, 2024). "Adjustment with only the transcriptome-derived naïve CD4 T cell proportions resulted in the most DMPs compared to any other model in the baseline to malaria and malaria to recovery contrasts." (PMID 38992677, 2024). "Memory CD4 T cells only had 2 deconvolution sensitive genes in the baseline versus malaria and malaria versus recovery contrasts." (PMID 38992677, 2024). "With HIV co-infection they are increasingly vulnerable to malaria-related complications because HIV-induced downregulation of CD4+ T cells and decreases in CD8+ T-cell counts." (PMID 39559371, 2024). "In some parasitic infectious diseases such as leishmaniosis or malaria, the efficacy of vaccines relies not only on the balance of cytokine production but also on the activation and induction of memory subsets of CD4+ and CD8+ T lymphocytes." (PMID 38396573, 2024). "The MCMV vaccine-expressing a malaria epitope prolongs survival of epitope-specific CD4 Teff and Tem." (PMID 37205446, 2023). "As IFN-γ-producing effector/effector memory cells play a key role in the induction and maintenance of long-term protection against malaria mediated by CD4+ T cells or CD8+ T cells, gated CD4+ and CD8+ splenocytes were analyzed for expression of CD62L and CD44." (PMID 37553591, 2023). "Through this analysis, we identified a population of activated, malaria-specific, interleukin-10 (IL-10) and interferon-gamma (IFNγ) expressing CD4+ T cells that were more common in primigravid versus multigravid women." (PMID 37634385, 2023). "Another study reported that during the blood stage of malaria, the parasite induces CD4+Foxp3+CD25+ regulatory T cells to release a fibrinogen-like protein 2 (sFGL2), resulting in immunosuppression, thereby enhancing the infection." (PMID 37219610, 2023). "It is mainly secreted by dendritic cells and macrophages, while CD4+ T cells also produce IL‐27 during chronic infection such as malaria and tuberculosis." (PMID 37855243, 2023). "Our data provide insight into the shifting quality of the malaria-specific CD4+ T cell response across pregnancies, and we identify malaria-specific CD4+ T cell features that correlate with protection against malaria in pregnancy." (PMID 37634385, 2023). "In these reports, the CD4+ T cell cytolytic clones were isolated from the animal model of malaria or human participants that received irradiated sporozoite immunizations." (PMID 38001069, 2023). "CD4 T cells play multiple essential roles in protection from malaria, including IFNγ mediated direct killing of parasites, and by providing help to B cells to produce antibodies required for protection." (PMID 37968278, 2023). "Together data is supportive of specific upregulation of a regulatory program within CD4 T cells during malaria." (PMID 37968278, 2023).
malaria (continued). "To measure malaria-specific CD4+ T cell activation, we stimulated PBMCs with VAR2CSA expressing CS2 Pf-iRBCs, PHA, or media, and analysed the expression of OX40 and CD137." (PMID 37634385, 2023). "We did not observe any significant correlations between percentages of OX40+ malaria-specific CD4+ T cells and VAR2CSA-specific antibody responses measured concurrently, similar to results of another study." (PMID 37634385, 2023). "Overall, this work provides insights into CD4+ T cell development during malaria that offer opportunities for creation of strategies to modulate CD4+ T cell functions and improve antiparasitic immunity." (PMID 36594463, 2023). "The presence of cytolytic CD4+ T cells in malaria-infected patients and mouse models of malaria was first reported several decades ago40,73." (PMID 38001069, 2023). "Regarding the adaptive immune response, it has already been reported that CD4+ T cells play a critical role in the response to the pre-erythrocytic stage of malaria." (PMID 36839519, 2023). "We show that P2RX7 induces T-bet expression and aerobic glycolysis in splenic CD4+ T cells that respond to malaria, at a time prior to Th1/Tfh polarization." (PMID 36993971, 2023). "T cells, particularly CD4+ T cells, are a critical component of the immune response to blood-stage malaria." (PMID 37812650, 2023). "We also noted higher frequency of HLA-DR+ CD4 T cells in protected children during the peak of the malaria season and comparable levels cytokine secretion after stimulation with malaria schizonts across all three time points." (PMID 37465667, 2023). "To investigate CD4 T cells transcriptionally during malaria, we subclustered CD4 T cells from PBMCs, with 9 subsets identified." (PMID 37968278, 2023). "In particular, we identified higher percentages of activated malaria-specific CD4+ T cells expressing OX40, CD137, and ICOS in primigravid compared with multigravid women." (PMID 37634385, 2023). "Together, these data suggest that percentages of malaria-specific AIM+ CD4+ T cells, AIM+ Tfh cells, as well as OX40+ICOS+ cells, are higher in primigravid compared with multigravid women." (PMID 37634385, 2023). "In contrast, multigravid women had higher percentages of malaria-specific, tumour necrosis factor-alpha (TNFα) -expressing CD4 T cells that correlated with protection from malaria in pregnancy." (PMID 37634385, 2023). "Malaria has been related to a higher CD4+ T-cell count suggesting enhanced levels of CD4 by low malaria parasitemia." (PMID 36600836, 2023). "It has been also reported that previous exposures to Plasmodium influenced the production of cytokines by adaptive immune cells (CD4+ T cells) and attenuated the semi-innate Vδ2+ γδ T cells in response to malaria." (PMID 36787308, 2023). "For example, abrogation of CD4+ T cells and γδ T cells in RAS-immunised mice resulted in a loss of malaria protection." (PMID 37195999, 2023). "Together these data are indicative of CD4 T cell activation dominated by Tr1 cells with increases suppressive function during malaria." (PMID 37968278, 2023). "To investigate malaria-specific CD4+ T cell function, we first used an activation-induced marker (AIM) among participants enrolled in the DPSP study." (PMID 37634385, 2023). "Given the higher gene expression of TSLP observed in parasitemic, primigravid women, and the documented role of TSLP in CD4+ T cell differentiation, we next investigated differences in malaria-specific CD4+ T cell subsets and response." (PMID 37634385, 2023). "Here we show that the MCMV vector can be used to specifically boost CD4 epitope-specific effector T cell responses, which is one of the primary gaps in our current malaria vaccine arsenal." (PMID 37205446, 2023). "We compared the frequency of ZEB2+ memory CD4+ T cells during the enrollment episode of clinical malaria to the frequency during a subsequent episode of clinical malaria between the two groups." (PMID 38001069, 2023).
malaria (continued). "P2RX7 amplifies the Th1 response to malaria by inducing metabolic reprogramming for aerobic glycolysis, which supplies the anabolic intermediates needed to support rapid CD4+ T cell growth and proliferation." (PMID 36993971, 2023). "Diseases caused by intracellular protozoan parasites such as malaria require dendritic cells and macrophages to present antigens that prime or expand IFN-γ+Tbet+CD4+ Th1 cells, which activate phagocytes to kill captured or resident pathogens." (PMID 36594463, 2023). "Decay of immunity, and failure to maintain Plasmodium-specific CD4 T cells make the development of an effective and long-lived malaria vaccine challenging." (PMID 37205446, 2023). "Regarding parasitic infections, the administration of α-GalCer with different Plasmodium spp.-derived antigens has been demonstrated to elicit both IFN-γ production and malaria-specific CD4+ T cells, leading to an increased anti-malaria immunity in mice." (PMID 38136283, 2023). "Together, these results suggest that primigravid women have a malaria-specific CD4+ T cell response that is skewed towards IL-10 and is associated with a higher risk of malaria in pregnancy." (PMID 37634385, 2023). "For example, CD4+ T cells support the B cell response to malaria, and the repressed CD4+ T cell response to P. chabaudi in TfrcY20H/Y20H mice presumably further constrained the B cell response." (PMID 37812650, 2023). "Within the CD4 T cell compartment, type 1 regulatory (Tr1) cells that co-produce IFNγ and IL-10 during malaria, dominate antigen-specific CD4 T cell responses in children in high endemic areas." (PMID 37968278, 2023). "The production of the antiinflammatory cytokine IL-10 and expression of coinhibitory receptors by parasite-specific CD4+ T cells are important components of the immune regulatory networks that arise during malaria." (PMID 37781920, 2023). "Control of intracellular parasites responsible for malaria requires host IFN-γ+T-bet+CD4+ T cells (Th1 cells) with IL-10 produced by Th1 cells to mitigate the pathology induced by this inflammatory response." (PMID 36594463, 2023). "Type I IFNs not only have potent antiviral activities, but also modulate CD4+ T cell responses during experimental and clinical malaria, including suppressing Th1 and Tfh cell responses." (PMID 37781920, 2023). "While IL-10 producing CD4 T cells have been well recognised in malaria, this study identifies B cells as a major source of IL-10 during human malaria." (PMID 37968278, 2023). "We report that the vaccine induces a CD4+ T-cell-dependent strain-transcending protective immunity in mice against challenge infection, which can be enhanced by subsequent exposure to malaria, thus holding promise for clinical development." (PMID 37962347, 2023). "Nonetheless, other immune cells are also likely to contribute to the development of sterilizing immunity to malaria, including the γδ T cells, CD4+ T cells, DCs, and NK cells." (PMID 37195999, 2023). "The incidence and effect of malaria in HIV patients gets tremendous when the immune gets compromised as evidenced from lower CD4 count." (PMID 35245289, 2022). "A CTLA-4+PD-1+ population of CD4+ T cells was identified in the blood of patients who had recently travelled to malaria-endemic regions and became infected." (PMID 36389662, 2022). "Upon intracellular staining of Foxp3, it was found that infection with lethal malaria parasite induced significantly higher frequencies of CD4+ICOS+Foxp3+Treg cells with nearly 50% of CD4+ICOS+ T cells expressed Foxp3 by day 10th post infection." (PMID 35109868, 2022). "T cells, especially CD4+ T cells, have been described to play an important role in limiting blood-stage malaria." (PMID 36094170, 2022). "At baseline (C-1), γδ T and CD4+ T cells constituted the majority of cells producing IFNγ or TNF upon PfRBC stimulation among malaria pre-exposed Africans." (PMID 35922467, 2022).